ALCAM (activated leukocyte cell adhesion molecule)
Diseases named in the same sentence as ALCAM in open-access papers (continued):
Sharing a sentence is not in itself a finding about the gene and the disease.
tumor (continued). "Overexpressed in a number of epithelial tumors and suggested to be an important prognostic marker of tumor progression, CD166 (i.e. ALCAM) appears to further segregate TG from NTG cells when used in combination with ESA and CD44." (PMID 18560594, 2008). "The activation of ALCAM (Activated Leukocyte Cell Adhesion Molecule) and CD6 signaling may suggest the enhancement of tumor cell adhesion and migration, which may help tumor cells infiltrate and metastasize to other tissues." (PMID 40932351, 2026). "The present work shows an immunosuppressive effect of CD318 but not ALCAM on tumor cells, hampering proliferative responses of T cells and reducing immune cell viability and frequencies of CD6+ lymphocytes on co-cultures." (PMID 40391211, 2025). "A hypoxic microenvironment promotes binding of HIF‐1α complex is demonstrated to the ALCAM promoter therefore increasing its expression in macrophages, and the ALCAMhigh macrophages co‐localize with exhausted CD8+ T cells in the tumor spatial microenvironment and promote T cell exhaustion." (PMID 38956900, 2024). "Of course, this process is not alone for ALCAM since other known ‘seed and soil’ receptors would also participate in the tumour-mesothelial interaction." (PMID 36614319, 2023). "Two of these ligands (ALCAM and VLA‐4) are particularly highly expressed in tumour cells, and the neutralisation of either ligand with antibodies has been found to significantly reduce tumour seeding in the brain." (PMID 37830128, 2023). "Interestingly, CD166/ALCAM is overexpressed in different cancer types and has been involved in some tumour-related processes, such as tumour progression or poor prognosis." (PMID 38139340, 2023). "In the majority of the SHH, Group 3, and Group 4 subgroup cases, no expression of ALCAM was observed in the tumor cells." (PMID 33270750, 2020). "Previous mouse models utilizing human PC-3 and LNCaP xenografts have demonstrated a role for tumor, but not host derived ectodomain ALCAM in influencing the tumor burden of subcutaneous and orphotopic xenographs." (PMID 31695844, 2019). "In the analysis of ALCAM transcripts, the level of the ALCAM gene methylation was significantly higher in negative ALCAM transcripts group in tumor tissues (p = 0.027)." (PMID 29315254, 2018). "The methylation status of the ALCAM gene was not significantly different between tumor and normal tissues." (PMID 29315254, 2018). "Tumor-promoting roles of MAP3K6, PAK1, ALCAM and ITGA6 have been reported, thus their upregulation may also function in the development of NASH-related HCC." (PMID 30367044, 2018). "According to the results of RT-PCR of ALCAM transcripts, the level of ALCAM transcripts was not significantly different between tumor and normal tissues (p = 0.716, data not shown)." (PMID 29315254, 2018). "In this study, we used an extracellular-ALCAM antibody to assess the non-cleaved protein expression by immunohistochemistry in two different tumor areas from 116 EEC primary tumors, i.e. at the superficial and the invasive front." (PMID 29682175, 2018). "Urine ALCAM levels were not significantly different between tumor stages but did show a significant positive trend (K-W, P = 0.058; J-T, P = 0.018), suggesting that ALCAM shedding increases with invasive progression." (PMID 27894096, 2017). "In summary, we show that although the histological detection of ALCAM within the tumor tissue correlates strongly with tumor stage in BCa, it does not appear to be prognostic of overall survival." (PMID 27894096, 2017). "Second, the monoclonal antibody, 1G3A, that is against the intracellular domain of ALCAM can only detect ALCAM in the cell lysate, indicating that ALCAM in the tumor cell conditioned media and urine is lacking this intracellular domain (1G3A)." (PMID 27894096, 2017). "ALCAM expression was not changed 3 weeks post tumor cell infusion for all dietary treatments except SeGP40, which increased expression of this adhesion molecule." (PMID 26706037, 2016).
tumor (continued). "ALCAM is localized at sites of lateral cell contacts in the pulmonary endothelium, and is therefore unlikely to mediate adhesions between circulating tumor cells and the endothelium." (PMID 20929568, 2010). "Additional control experiments showed that anti-ALCAM antibodies did not alter the total number of ALCAM-negative MDA-MB-435 tumor cells retained in the rat lung." (PMID 20929568, 2010). "On the contrary, ALCAM expression had no significant impact on the number of single MDA-MB-435 tumor cells adhering to the endothelial wall, and anti-ALCAM antibody did not influence this number." (PMID 20929568, 2010). "The promoter contains multiple cis-active elements including a functional p65 NF-κB motif, and it harbors an extensive array of CpG residues highly methylated exclusively in ALCAM-negative tumor cells." (PMID 20929568, 2010). "Sequencing revealed that virtually all CpG islands in the ALCAM promoter are methylated in tumor cells lacking ALCAM expression." (PMID 20929568, 2010). "Despite this significance, mechanisms that regulate ALCAM gene expression and ALCAM's role in adhesion of pre-metastatic circulating tumor cells have not been defined." (PMID 20929568, 2010). "Our findings provide new mechanistic insights on ALCAM that can be developed further to alter its negative influence in tumor cell progression." (PMID 20929568, 2010). "However, FSTL1+ tumor cells, which were most abundant in the PD-1+SMI group, expressed high levels of the lung CSCs marker genes CD44 and ALCAM, and the CSCs score was significantly higher than those in the other subclusters, except for NEAT1+ and XIST+ tumor cells." (PMID 37430270, 2023). "Therefore, different molecules on the EV surface (including ALCAM and ADAM17) are involved in the interactions between tumor-derived EVs and recipient cells and the adhesive capacity of these molecules may be subjected to additional regulation by EV CD9." (PMID 35628559, 2022). "Thus, the poor prognosis in patients with marker CD44+ABCG2-ALCAM- or CD44-ABCG2+ALCAM- might be related to the more active biological processes in LCSCs and greater tumor dedifferentiation." (PMID 36613925, 2022). "However, the functional significance of ALCAM in cancer is not consistent, with the differences depending on both the cancer type and tumor microenvironment." (PMID 33270750, 2020). "The presence of this ALCAM-Fc chimera was found to enhance the tubule formation capacity of HECV human endothelial cells, potentially indicating a pro-angiogenic effect, which could support advanced tumor growth and aid metastatic dissemination." (PMID 31695844, 2019). "Because tumour development is largely orchestrated by inflammation, MSCs exhibit upregulation of various chemokine receptors (CCR1, CXCR5 and CCR2) and adhesion molecules (ALCAM, P-selectin and integrins) to facilitate extensive tropism towards specific tumour sites." (PMID 31908585, 2019). "Interestingly, the association between the ALCAM gene methylation and the levels of ALCAM transcripts was only significant in tumor tissues, but not normal tissues in this study." (PMID 29315254, 2018). "Most importantly, ALCAM protein expression was not a significant predictor of overall survival when treated as a continuous covariate and adjusted for age, gender, tumor stage and lymph-node status by multivariable Cox regression analysis (adjusted HR, 1.00; 95% CI, 0.99–1.02; p = 0.843)." (PMID 27894096, 2017). "Basal-like status was associated with ALCAM expression (p = 0.01) however in this model, age (under or above 50 years), histological grade (poorly and well-moderately), tumor size [large (>2 cm) and small (≤2 cm)], lymph node status, did not contribute to ALCAM expression." (PMID 25255861, 2014).
tumor (continued). "There is an evidence that 14G2a antibodies could cross-react with highly glycosylated ALCAM (CD166) adhesion molecule, which is expressed in different tissues, mainly on cells of the immune system, and this molecule does not exhibit tumor association." (PMID 24773917, 2014). "With regard to cellular localization, in MTC the surrounding non-tumor tissue and the corresponding tumor tissue showed membranous positive immunostaining, as in the surrounding non-tumor tissue of PTC; while in PTC tumor tissue ALCAM staining was localized at the membrane and in the cytoplasm." (PMID 21364949, 2011). "Subsequent studies showed that patients with the lowest level of ALCAM transcripts develop skeletal metastasis, that low ALCAM correlated with an aggressive tumor phenotype and significantly negative correlation between ALCAM expression and tumor diameter and grade." (PMID 20929568, 2010). "In a further sub-group analysis, the six patients with partial membranous expression had a significant shorter median overall (median: 10.9 vs 18.7 months, P=0.03) and tumour recurrence-free survival (median: 6 vs 15 months, P=0.02) compared with tumours with non-membranous ALCAM staining." (PMID 19603023, 2009). "However, ALCAM silencing did not affect survival or the formation of leptomeningeal dissemination in an orthotopic mouse model, but did induce a malignant phenotype with increased tumor cell invasion at the dissemination sites (P = 0.0029)." (PMID 33270750, 2020). "In addition, we immunohistochemically analyzed tumor tissues of advanced breast cancer patients, and found that accumulation of ALCAM+ cells (possibly including the sMSCs) significantly correlates with FSTL1 expression level in tumor portions, but not in the adjacent normal counterparts." (PMID 25883937, 2015). "Nevertheless, not only did the majority of primary PAC lesions express ALCAM, but metastatic and recurrent lesions also showed a medium to strong expression (lymph node metastases 46%, n = 50; distant metastases 85%, n = 7; recurrent tumor lesions 67%, n = 15, data not shown)." (PMID 22745698, 2012). "Injection of 1 × 105 ALCAM knockdown GCTB28 cells showed no tumor formation at different time points (n = 0/5 each), whereas injection of 2.5 × 104 GCTB28 cells without ALCAM knockdown induced tumor formation in the second month after inoculation (n = 4/5)." (PMID 29463803, 2018). "Furthermore, multivariable Cox regression analysis reveals that ALCAM gene expression fails to reach significance as an independent predictor of 3-year overall survival after adjusting for available covariates including age, gender and tumor stage (adjusted HR, 1.26; 95% CI, 0.94–1.68; p = 0.118)." (PMID 27894096, 2017). "A trend toward higher levels of expression of ALCAM, CD24, and CD44, but not PROM1, was observed in CXs derived from D61540 when compared with their parental tumor." (PMID 24278200, 2013). "Unlike what was observed for CD6, confronting PBMCs with tumor cell lines does not modify CD5 expression on immune cells, which suggests that despite its high structural homology with CD6, neither CD318 nor ALCAM had an impact on CD5 expression." (PMID 40391211, 2025). "As examples, the only significant gene in the epithelial compartment, ALCAM was overexpressed in the epithelial component of Gleason 8 tumors, and the stromal gene SULF1 was highly expressed in stroma adjacent to high-grade, but not low-grade tumor." (PMID 28871082, 2017). "Most notably we did not detect ALCAM protein in MDA-MB-435 and FEMX-I tumor cells." (PMID 20929568, 2010).
cancer (205 papers, 2009 to 2025). A tumor composed of atypical neoplastic, often pleomorphic cells that invade other tissues. "Abnormal expression of ALCAM has been described in various tumors and is associated with cancer progression." (PMID 39944833, 2025). "In cancer, ALCAM has been linked to poorer prognosis and higher metastatic risk in some cancers such as breast, thyroid, head and neck and liver cancer." (PMID 36275816, 2022). "In colorectal cancer, high ALCAM shedding is associated with cancer progression and correlates with poor patient outcomes, being significantly increased in stage II, III, and IV patients." (PMID 35628559, 2022). "Hypothetical activation of ALCAM results in the activation of all the signaling pathways associated with cancer." (PMID 36009530, 2022). "Deficiency of stromal ALCAM has been indicated in aiding the homing of cancer cells to lung and lung tissues and accelerating both spontaneous and systemic metastasis." (PMID 34680335, 2021). "This contrasts with the high number of studies reporting association of CD166/ALCAM expression with grade, stage and invasiveness of different carcinomas." (PMID 34070159, 2021). "Activated Leukocyte Cell Adhesion Molecule (ALCAM) has been linked to the progression of numerous human cancers, where it appears to play a complex role." (PMID 31695844, 2019). "ALCAM has been implicated to influence cellular traits associated with cancer progression in vitro and in vivo, though there is some conflict within the literature." (PMID 31695844, 2019). "A multivariate statistical analysis revealed that ALCAM-negative cases harbored a 1.876-fold higher risk of cancer recurrence (p = 0.022, 95% confidence interval 1.096–3.211) than ALCAM- positive cases, and ALCAM was an independent prognostic factor for TTR." (PMID 29375378, 2017). "ALCAM is increased in cancers and is associated with metastasis, further suggesting that higher expression of this protein facilitates cell migration into tissue." (PMID 23922698, 2013). "ALCAM has also been implicated in pathological states, such as cancer metastasis, but its role remains somewhat confusing." (PMID 22745734, 2012). "An altered expression of the activated leukocyte cell adhesion molecule (ALCAM) is associated with cancer progression in various cancer types." (PMID 22475274, 2012). "ALCAM, a member of the immunoglobulin superfamily, has been implicated in numerous developmental events and has been repeatedly identified as a marker for cancer metastasis." (PMID 22745734, 2012). "Alterations in expression of ALCAM have been reported in several human tumors, and cell adhesion functions have been proposed to explain its association with cancer." (PMID 21364949, 2011). "Lowering ALCAM expression in this type of cancer is associated with poor prognosis for patients." (PMID 36547538, 2022). "Likewise, the group of patients with cytoplasmic/nucleus beta-catenin and cytoplasmic ALCAM staining also linked to nodal metastasis and late stage of the cancers." (PMID 34680335, 2021). "Alterations in ALCAM expression have been reported and associated with the progression or prognosis of various human cancers including, breast, melanoma and gastric cancer, however there are again contrasting reports within the literature." (PMID 31695844, 2019). "Interestingly, in breast, ovarian and oral cancers, high membrane and cytoplasmic ALCAM expression is associated with poor outcomes." (PMID 28537909, 2017). "Patient selection with higher CD318+ and lower ALCAM+ tumors will be a critical step to improving the use of itolizumab as an immunotherapy against cancer." (PMID 40391211, 2025). "Our data highlighted a significant enrichment of certain cellular adhesion molecules, including MCAM, EpCAM, ICAM-1, EGFR, and ALCAM, in cancer EVs relative to hTERT-immortalized MSC EVs." (PMID 38786083, 2024). "Several groups have reported that ALCAM/CD166 is expressed in TEVs produced by different types of cancer cells." (PMID 38542421, 2024).
cancer (continued). "ALCAM proteins on cancer cells act as ‘seed’ receptor, and on peritoneal mesothelial cells function as a ‘soil’ receptor, through its homotypical protein–protein interactions." (PMID 36614319, 2023). "Among these proteins, CD166 antigen (ALCAM/CD166) is shown to be a potential cancer stem cell marker." (PMID 37775701, 2023). "A soluble ALCAM (sALCAM) was found to be able to inhibit the adhesiveness between cancer cells and mesothelial cells, mechanistically behaving like a SRC kinase inhibitor." (PMID 36614319, 2023). "To monitor if the changes of ALCAM in these cells impacted the interaction between cancer cells and mesothelial cells, we used the electric cell-substrate sensing (ECIS) as a method to trace the dynamic interactions between the two cell types." (PMID 36614319, 2023). "Using these cell models, we studied the roles of ALCAM in cancer cells and mesothelial cells during metastasis and the interplay between these cells and disclosed the potential role the SRC kinase in this interaction." (PMID 36614319, 2023). "By using a blocking monoclonal antibody specific to the β1 integrin subunit (mAb Lia1/2), we confirmed that, in parallel to ALCAM-mediated interactions, members of the β1 integrin subfamily are also involved in EV interactions with cancer cells." (PMID 35628559, 2022). "Our results show that the adhesion molecule ALCAM/CD166 participates in the “binding/docking” of cancer-derived EVs and in their subsequent uptake by recipient cancer and peritoneal mesothelial cells." (PMID 35628559, 2022). "As a valuable prognostic marker of cancers, ALCAM indicated the clinical stage, grade, and the invasiveness of cancers." (PMID 36482940, 2022). "In conclusion, we established that ALCAM/CD166 is involved in cancer-derived EV interactions with recipient cancer and peritoneal mesothelial cells and in their subsequent cellular uptake by these cells." (PMID 35628559, 2022). "In pancreatic cancer, patients whose circulating cancer cells have high levels of ALCAM, tend to have significantly shorter survival." (PMID 36275816, 2022). "The role of ALCAM as a biomarker for inflammation, angiogenesis, diagnosis, prognosis, and treatment response in various cancers has been established." (PMID 35720325, 2022). "When ALCAM molecules are expressed both on EV and cell surfaces, they can mediate the binding and subsequent uptake of cancer-derived EVs through homophilic ALCAM-ALCAM interactions." (PMID 35628559, 2022). "We established that the adhesion molecule ALCAM/CD166 is involved in the interaction of cancer-derived EVs with recipient cancer cells (a process termed “EV binding” or “EV docking”) and in their subsequent uptake by these cells." (PMID 35628559, 2022). "The positivity of ALCAM staining was found to be an independent factor of tissue invasion of cancer." (PMID 34680335, 2021). "ALCAM has multiple and diverse roles in various physiological and pathological conditions, including inflammation and cancer." (PMID 34680335, 2021). "Truncated ALCAM, also referred to as soluble ALCAM, has been indicated in possible therapeutic applications in cancers in which ALCAM is a promoting factor in their development and progression." (PMID 34680335, 2021). "In a small size study of patients with pancreatic ductal adenocarcinoma, Amantini and colleagues have shown that when circulating cancer cells had high levels of ALCAM, patients tend to have significantly shorter survival." (PMID 34680335, 2021). "Given the significant implications of ALCAM in cancer, the detection of soluble ALCAM as a potential serum biomarker (or through other minimally invasive detection of ALCAM) has gained much scientific interest and focused investigation." (PMID 34680335, 2021). "In this case, the pro-metastatic miR-214 and anti-metastatic miR-145b act as a dual in down- or upregulating ALCAM in cancer cells in this process." (PMID 34680335, 2021).